MCPH1 (microcephalin 1)
Diseases named in the same sentence as MCPH1 in open-access papers (continued):
Sharing a sentence is not in itself a finding about the gene and the disease.
tumor (continued). "MCPH1 gene deletions were seen in 5–15% of human cancers, depending on the anatomic site of the tumor." (PMID 32681070, 2020). "We further observed that overexpression of MCPH1 decreased cellular proliferation, anchorage-independent growth in soft agar, cell invasion and tumor size in nude mice, indicating its tumor suppressive function." (PMID 23472065, 2013). "In summary, the results of the present study have suggested that the primary microcephaly gene MCPH1 shows several hallmarks of TS genes and functions as a tumor suppressor in OSCC, in addition to its role in brain development." (PMID 23472065, 2013). "The results showed a significant decrease in number of colonies in MCPH1 overexpressing B1 and B9 clones as compared to KB cells and, V2 and V4 clones, suggesting its tumor suppressive function." (PMID 23472065, 2013). "We have shown that the tumor suppressive function of MCPH1 in KB cells is due to induction of apoptosis as characterized by elevated CASP3 activation, which is an important event in apoptosis." (PMID 23472065, 2013). "These 24 matched normal and tumor samples were considered as a separate set and the relative expression of MCPH1 in tumors was compared with that in matched normal tissues." (PMID 23472065, 2013). "The results showed that MCPH1 exhibits three hallmarks of tumor suppressors, such as the presence of LOH, somatic mutations and promoter methylation in tumor samples, although at a lower rate." (PMID 23472065, 2013). "The observation of decreased cell proliferation and growth of colonies in soft agar of B1 and B9 cells prompted us to study the tumor suppressive function of MCPH1 in nude mice." (PMID 23472065, 2013). "The studies conducted in KB cells demonstrate that MCPH1 possesses tumor suppressive properties due to its ability to reduce growth in vitro and in vivo." (PMID 23472065, 2013). "Our study indicates for the first time that, in addition to its role in brain development, MCPH1 also functions as a tumor suppressor gene and is regulated by miR-27a." (PMID 23472065, 2013). "In the remaining pair (pt# 128), the level of miR-27a was downregulated in tumor, but the level of MCPH1 remained unchanged between normal and tumor tissues." (PMID 23472065, 2013). "The visual observation of tumor regression on MCPH1 overexpression was further validated by examining the paler necrotic regions within hematoxylin and eosin stained histological sections of the xenografts." (PMID 23472065, 2013). "Whereas RAD50 c.687delT variant did not associate with any clinical tumor features, MCPH1 c.909_921del carriers had a significant enrichment of multifocal tumors (38% vs. 16% in non-carriers)." (PMID 40009290, 2025). "Moreover, the change in both MCPH1/BRIT1 and ATM together was significantly associated with an increased in tumour grade." (PMID 36845691, 2023). "This region is important in disease discovery due to its association with many mutations that arise in MCPH1/BRIT1; furthermore, many studies have suggested there is a link between N-terminal domains and determining brain size, gonad development and tumour progression." (PMID 36845691, 2023). "The downregulation of MCPH1/BRIT1 correlated with increased tumour grade." (PMID 36845691, 2023). "MCPH1/BRIT1 is also known as a tumour suppressor in different types of human cancer." (PMID 36845691, 2023). "Furthermore, we confirmed three genes (ATM, NBN and MCPH1) to be downregulated in clinical CRPC tumor samples in our in vitro models." (PMID 36139600, 2022). "Nonetheless, a high tumour incidence of these Mcph1-Δ and Mcph1-ΔBR1 mice supports tumour repressor function of MCPH1, corresponding to previous studies showing that MCPH1 is down-regulated or mutated in human cancer patients, including those suffering ovarian cancer." (PMID 33542216, 2021). "In addition, MCPH1 functions as a tumor suppressor with roles in DNA damage repair, checkpoint activation, and apoptosis." (PMID 30303738, 2019).
tumor (continued). "Similarly, miR-27a was shown to downregulate expression of and to inhibit tumor suppressor function of microcephalin 1 (MCPH1) in OSCC cells." (PMID 26504785, 2015). "A low level of MCPH1 promoter methylation was also observed in 4/40 (10%) tumor samples." (PMID 23472065, 2013). "We were further interested in understanding the mechanism of tumor suppression by MCPH1." (PMID 23472065, 2013). "Finally, MCPH1 has been proposed to function as a tumor suppressor gene that contributes to both cancer initiation and cancer progression in a variety of cancer lineages." (PMID 23516444, 2013). "Furthermore, when studying the MCPH1 c.909_921del carriers in more detail, a large proportion (13/34) had also in situ growths in addition to the invasive tumor, six of these also having the multifocal tumor type." (PMID 40009290, 2025). "Consequently, future studies are warrants to examine MCPH1/BRIT1 as a tumour suppressor." (PMID 36845691, 2023). "In addition, as expected for TS genes, MCPH1 overexpression reduced cell proliferation, colony formation in soft agar assay and tumor growth in nude mice, suggesting that it indeed functions as a tumor suppressor gene, in addition to its role in brain development." (PMID 23472065, 2013). "This was confirmed in a study conducted on various types of tumours, which identified MCPH1/BRIT1 gene deletions in 5–15% of cancers." (PMID 36845691, 2023). "Recent studies have further documented that Microcephalin 1 (MCPH1) dysfunction is highly correlated with tumorigenesis and prognostic survival, indicative of a tumor suppressor function." (PMID 32735676, 2020). "BRIT1 protein (also known as MCPH1) contains 3 BRCT domains which are conserved in BRCA1, BRCA2, and other important molecules involved in DNA damage signaling, DNA repair, and tumor suppression." (PMID 20107607, 2010). "MCPH1 staining intensities in pre‐NACT tumour samples, ranging from negative and weak to moderate and strong." (PMID 39775836, 2025). "However, MCPH1 and MCPH15 are downregulated in tumor tissues or cancer cell lines and are considered as novel tumor suppressor genes." (PMID 32121580, 2020). "Interestingly, five genes with concordance between CNLs and down-regulation were observed in more than 50 tumor samples, including MTAP (216 samples), PTEN (143 samples), MCPH1 (86 samples), SMAD4 (63 samples), and MINPP1 (51 samples)." (PMID 27929028, 2016). "Since TS genes are expected to show downregulation in a majority of the tumor samples, if not in all, we sought to determine the levels of MCPH1 transcript and protein in OSCC samples." (PMID 23472065, 2013). "The fourth OSCC sample (pt# 80) showed promoter methylation of CpGII, but there was no change in the transcript levels of MCPH1 between the matched normal and tumor samples." (PMID 23472065, 2013). "In order to see if the region harboring the MCPH1 gene shows LOH in OSCC samples, we performed LOH study in a panel of 81 matched blood/normal oral and tumor tissues using three microsatellite markers (viz., D8S1819, D8S277 and D8S1798) flanking the MCPH1 locus." (PMID 23472065, 2013). "However, the four available Mcph1 mutant mouse lines have not been reported to show any excess of tumours, although none have been systematically aged and examined appropriately to detect tumours." (PMID 23516444, 2013).
cancer (27 papers, 2010 to 2026). A tumor composed of atypical neoplastic, often pleomorphic cells that invade other tissues. "High levels of chromosomal rearrangements were observed for carriers of MCPH1 mutation, indicating that increased genomic instability and cancer development caused by MCPH1 haploinsufficiency." (PMID 39775836, 2025). "Microcephaly 1 (MCPH1) plays diverse roles in cell cycle ‐checkpoint and DNA repair regulation, and its mutation has been found to lead to genomic instability and cancer development." (PMID 39775836, 2025). "Deletion of MCPH1 is also associated with centrosome amplification—a common feature in different cancers which correlates with worse outcomes." (PMID 39594644, 2024). "The MCPH1/BRIT1 gene contains a single nucleotide repeat (A9), which is a mutation target in cancers with MSI that inhibits the TSG activities contributing to tumorigenesis." (PMID 36845691, 2023). "This study provides additional insight into the clinically-relevant causes of CA in human cancer, revealing MCPH1 deletion as a common and penetrant driver of CA." (PMID 32681070, 2020). "MCPH1 is on chromosome 8p23.1, a region of the genome that is commonly deleted in human cancer, is occasionally associated with gains of chromosome 8q, and portends worse outcomes." (PMID 32681070, 2020). "Our study also revealed MCPH1 deletion as a cause of chromosomal instability in human cancer, as demonstrated by frequent aberrant mitoses." (PMID 32681070, 2020). "We conclude that loss of MCPH1 is common in human cancer, and depletion of MCPH1 in vitro causes CA." (PMID 32681070, 2020). "In order to exclude the presence of any other known cancer predisposing gene mutations in MCPH1 c.904_916del carriers, all 21 index cases were analyzed using TruSight One Sequencing panel (Illumina)." (PMID 26820313, 2016). "MCPH1 is expressed in many other tissues, and mutations in MCPH1 have been discovered in cancerous tumors." (PMID 21492470, 2011). "These previous studies suggest a rationale to use ICIs with MCPH1/BRIT1-deficient cancers." (PMID 36845691, 2023). "MCPH1 is also responsible for centrosome amplification, which is a common hallmark of many cancers." (PMID 35053391, 2022). "Herein we provide evidence that one mediator of the phenotype observed in 8p-deleted cancers is MCPH1, which may cause CA and chromosomal instability in 8p-deleted cancers." (PMID 32681070, 2020). "These subsequent studies on MCPH1 c.904_916del carriers could serve as a model for somatically MCPH1 deficient cancers as well." (PMID 26820313, 2016). "Mutation carriers exhibited significant increase in genomic instability assessed by cytogenetic analysis for spontaneous chromosomal rearrangements in peripheral blood lymphocytes (P = 0.0007), suggesting an effect for MCPH1 haploinsufficiency on cancer susceptibility." (PMID 26820313, 2016). "Therefore, reduction or mutation in MCPH1/BRIT1 could progress to defects in DNA repair and subsequently to cancer." (PMID 36845691, 2023). "Our analysis of alterations in centrosome genes and in vitro validation of the most common alterations demonstrated that MCPH1 deletion occurs in up to 10% of human cancers, depending on the disease site, and causes CA." (PMID 32681070, 2020). "MCPH1 deletion as a cause of CA will need to be validated in additional cohorts of primary human cancers." (PMID 32681070, 2020). "However, for the majority (20/21) of MCPH1 c.904_916del carriers the possibility that other known cancer predisposition mutations could explain their cancer phenotype was excluded." (PMID 26820313, 2016). "Given that HRR-defective cancer cells can be killed via synthetic lethal approaches, MCPH1 thus represents an attractive target in cancer therapy." (PMID 41931484, 2026).
cancer (continued). "High TTK and low MCPH1 protein expression was significantly correlated, highlighting TTK's potential as a biomarker for BC and a therapeutic target for MCPH1‐deficient cancer cells." (PMID 39775836, 2025). "MCPH1 is downregulated in different types of human cancers, including colorectal (10%), ovarian (8%), breast (7%), lung (7%), and other cancer types." (PMID 39594644, 2024). "MCPH1/BRIT1 expression was associated with overall survival (OS) in 57% (12/21) and relapse-free survival (RFS) in 33% (7/21) of cancer types." (PMID 36845691, 2023). "A small prostate study showed a reduction in MCPH1/BRIT1 protein levels in cancer samples compared to normal tissues." (PMID 36845691, 2023). "In conclusion, the common findings of the role of MCPH1/BRIT1 in tumorigenesis in various types of cancer, is that the loss of MCPH1/BRIT1 gene plays a key role in promoting genome instability and mutations, which is one of cancer’s hallmarks." (PMID 36845691, 2023). "This provides a new biological foundation for dramatically expanding PARPi’s therapeutic potential in various types of cancer with depletion in MCPH1/BRIT1." (PMID 36845691, 2023). "In these cancer cells, MCPH1 overexpression promoted cell apoptosis due to an increase in the Bax and active caspase-3 protein levels, as well as a decrease in the level of Bcl-2." (PMID 35053391, 2022). "We conclude that loss of MCPH1 is common in human cancer and is likely to be a cause of CA." (PMID 32681070, 2020). "Some MCPH-associated genes, such as MCPH1, MCPH2, MCPH12, MCPH17, and MCPH20, regulate both neuroprogenitor and cancer cell proliferation through regulation of the cell cycle and cell division." (PMID 32121580, 2020). "Reduced MCPH1 mRNA expression and ASPM mRNA over-expression have been implicated in the development of human carcinomas." (PMID 24830737, 2014). "Thus, Mcph1 has attracted intense research interestdue to its crucial role in neurogenesis and cancer suppression." (PMID 39280843, 2024). "The molecular effects of MCPH1 dysfunction in cancer are not fully understood." (PMID 39594644, 2024). "Blood samples from MCPH1/BRIT1 mutation carriers also demonstrated high levels of chromosomal rearrangements suggesting MCPH1/BRIT1 haploinsufficiency causes increased genomic instability and cancer susceptibility." (PMID 36845691, 2023). "Loss of MCPH1/BRIT1 causes a decrease in chromatin relaxation through the reduced MCPH1-SWI/SNF interaction which could lead to cancer development." (PMID 36845691, 2023). "In this review we are interested in MCPH1/BRIT1 expression levels and its association with tumorigenesis in various forms of cancer, whether at the DNA, RNA or protein level." (PMID 36845691, 2023). "However, we did identify MCPH1 deletion as one genetic cause of CA, with deep deletions present in up to 10% of cancers depending on disease site, and validated that this deletion is sufficient to cause CA in model systems." (PMID 32681070, 2020). "Therefore, deletion of MCPH1, either one or both copies, is responsible for CA in at least some cancer cell lines." (PMID 32681070, 2020). "Hypermethylation of DNA damage-induced cellular response gene MCPH1 could also provide cancer cells with a safeguard against cell death mechanisms." (PMID 32051475, 2020). "Family history of cancers of MCPH1 c.904_916del positive index casesa." (PMID 26820313, 2016). "Genomic aberrations at the MCPH1 locus have been reported previously in cancers." (PMID 23472065, 2013). "Hence, MCPH1/BRIT1 deficiency induces genomic instability and enhances cancer risk." (PMID 36845691, 2023). "However, families harboring MCPH1 pathogenic variants do not seem to manifest increased cancer susceptibility." (PMID 35456440, 2022). "Taking all these data into account, we identified the following candidates as potential causes of CA in human cancer: gain of function of CEP19, CEP72, CTNNB1, PTK2, NDRG1, SPATC1, TBCCD1; and loss of function of CEP76, MCPH1, NEURL4, NPM1." (PMID 32681070, 2020).
cancer (continued). "However, MCPH1 knockout mouse models or the microcephaly patients exhibit no susceptibility to cancers." (PMID 23472065, 2013). "Furthermore, there is anecdotal evidence that the incidence of cancer in MCPH1 patients is low." (PMID 23516444, 2013). "The next steps to study the potential of MCPH1 in cancer therapy should address the mapping and characterization of MPCH1 expression levels in several cancer types with different molecular backgrounds and their response to TOP2A catalytic inhibition." (PMID 39885205, 2025). "In general, developments in cancer treatment have resulted in better patient outcomes; given the clinical relevance of MCPH1/BRIT1 expression we anticipate that MCPH1/BRIT1 defective patients would benefit from targeted therapies." (PMID 36845691, 2023). "It is also interesting to note that, in addition to MCPH1, few other MCPH genes have shown relevance in human cancers." (PMID 23472065, 2013). "It is therefore not surprising to note that MCPH1, required for the maintenance of centrosome number, has a role in development of cancers." (PMID 23472065, 2013). "In line with this notion, MCPH1 appears to assume multifaceted functions, including but not limited to: brain development, DNA damage repair, chromosome condensation, cancer, and germline function, as reviewed here and elsewhere." (PMID 25870538, 2015). "However, one caveat to our study is that MCPH1 deletion may be a passenger event rather than a driving event in human cancer." (PMID 32681070, 2020).
neurodevelopmental disorder (6 papers, 2016 to 2024). A behavioral and cognitive disorder with onset during the developmental period that involves impaired or aberrant development of intellectual, motor, or social functions. "MCPH1 has been identified as the causal gene for primary microcephaly type 1, a neurodevelopmental disorder characterized by reduced brain size and delayed growth." (PMID 38731817, 2024). "MCPH1, or BRIT1, is often mutated in human primary microcephaly type 1, a neurodevelopmental disorder characterized by a smaller brain size at birth, due to its dysfunction in regulating the proliferation and self-renewal of neuroprogenitor cells." (PMID 35053391, 2022).
Cardiovascular disease (1 paper, 2024). "Among these, 10 regions, proximal to or within the genes OVAAL, BMP3, RIOK1, AC096553.5, MCPH1, KCNU1, GLIS3, TUT7, TRIB3, and SYNDIG1, represent novel associations with MI and have not been previously linked to Cardiovascular disease (CVD)-related traits." (PMID 38725839, 2024).
genetic disorder (1 paper, 2010). "This defect resembles that described for PCC syndrome a human genetic disorder caused by MCPH1 mutations." (PMID 20169082, 2010).
MCPH1 also shares sentences with these, for which no sentence is quoted: Depression (2 papers); Intellectual disability (2); melanoma (2); nervous system disorder (2); Seckel syndrome (2); Alzheimer disease (1); Anxiety (1); Baraitser-Winter syndrome (1); bladder urothelial carcinoma (1); brain cancer (1); cervical squamous cell carcinoma (1); cervical tumour (1); cognitive disorder (1); colorectal adenocarcinoma (1); congenital anemia (1); endometrial tumors (1); Epileptic encephalopathy (1); Gorlin syndrome (1); head-neck squamous cell carcinoma (1); Klinefelter syndrome (1); Lissencephaly (1); liver cancer (1); Lynch-like syndrome (1); male infertility (1); MEGDEL syndrome (1); metastasis (1); Miller syndrome (1); multiple myeloma (1); Nijmegen breakage syndrome (1); oesophageal adenocarcinoma (1).
A further 18 diseases each share a sentence with MCPH1 in 1 paper.